IL17A (interleukin 17A)
Diseases named in the same sentence as IL17A in open-access papers (continued):
Sharing a sentence is not in itself a finding about the gene and the disease.
cervical carcinoma (59 papers, 2008 to 2026). A carcinoma arising from either the exocervical squamous epithelium or the endocervical glandular epithelium. "The latest meta-analysis with rs3748067 variant in the IL-17A gene reported that it was correlated with cervical carcinoma, with T allele carriers depicting an enhanced risk." (PMID 38816694, 2024). "Although previous studies have evaluated the correlation of IL-17A gene rs3748067 polymorphism with the susceptibility of breast and cervical cancers, the results were incosistent." (PMID 38816694, 2024). "Our study revealed a statistically significant link between IL-17A gene rs3748067 variant and cervical cancer." (PMID 38816694, 2024). "In contrast, activation of MMPs via p38/NFκB pathway with inflammatory cytokines like interleukin 17A (IL-17A), is associated with the invasion of cervical cancer cells, making IL-17A another potential prognosis marker of CESC." (PMID 34174910, 2021). "In the present study, we found that the rs2275913 of IL17A was correlated to the risk of cervical cancer." (PMID 23049595, 2012). "Although the presence of Th17 cells in situ was linked with cervical cancer progression, and IL‐17A was found to upregulate MMP‐2 and MMP‐9 expression favoring migration of cervical cancer cell lines, Th17‐induced mechanisms underlying cervical cancer metastases are not reported so far." (PMID 37899663, 2024). "Therefore, we conducted the present case-control study to analyze the association of the common SNP in the IL-17 A (rs3748067) gene with the susceptibleness of breast and cervical cancer." (PMID 38816694, 2024). "Therefore, the main purpose of this study was to investigate the regulatory effect of IL-17A on M2 macrophage polarization and the underlying mechanism in cervical cancer development." (PMID 38430256, 2024). "Therefore, this study was conducted to investigate the regulatory effect of IL-17A on M2 macrophage polarization and the underlying mechanism in cervical cancer development." (PMID 38430256, 2024). "For evaluating the hypothesis, we investigated the association of IL-17A rs3748067 polymorphism with the susceptibility of both breast and cervical cancer." (PMID 38816694, 2024). "Furthermore, the IL17A SNP (rs2275913) was significantly associated with the risk of developing cervical cancer." (PMID 36556060, 2022). "In conclusion, the current findings indicate that the polymorphism of IL17A may influence the susceptibility to cervical cancer in the Chinese population." (PMID 23049595, 2012). "However, our study has identified the link of IL-17A rs3748067 variant with cervical carcinoma and we are hopeful that our findings will have an impact on further studies that may result in stronger evidence." (PMID 38816694, 2024). "For this purpose, we co-cultured the PMA-stimulated THP-1 cells with the conditioned medium of cervical cancer cells treated with either PBS or IL-17A, resulting in the induction of M2 type macrophages." (PMID 38430256, 2024). "Thereafter, rescue assays were carried out to verify the regulatory function of Oct4 and IL-17A on cervical cancer cell behaviors." (PMID 38430256, 2024). "As evidenced by RT-qPCR and ELISA, we demonstrated that Oct4 knockdown can reduce IL-17A expression in cancer cells, suggesting that Oct4 regulates the expression and production of IL-17A in cervical cancer." (PMID 38430256, 2024). "Subsequently, through a co-culture system of cancer cells and macrophages, we found that overexpression of IL-17A can promote M2 macrophage polarization in cervical cancer." (PMID 38430256, 2024). "Taken together, this study confirmed that Oct4 transcriptionally activates IL-17A to regulate the p38 signaling pathway and promotes M2 macrophage polarization thereby promoting cervical cancer metastasis." (PMID 38430256, 2024). "Firstly, we detected IL-17A expression in human cervical cancer tissues and human normal adjacent tissues." (PMID 38430256, 2024).
cervical carcinoma (continued). "In this study, we have also tried to compare the frequency of genotypes of IL-17A rs3748067 between breast and cervical cancer patients." (PMID 38816694, 2024). "Collectively, these data indicated that Oct4 overexpression can promote IL-17A levels in cervical cancer." (PMID 38430256, 2024). "Oct4 triggers IL-17A to facilitate the polarization of M2 macrophages, which promotes cervical cancer cell metastasis." (PMID 38430256, 2024). "On the other hand, the analysis of IL-17A rs3748067 with cervical cancer demonstrated that CT genotype showed a significant association (CT vs. CC: OR=1.79, p=0.021)." (PMID 38816694, 2024). "We further tested IL-17A expression in primary and metastatic tissues of cervical cancer, and the outcomes confirmed the significant overexpression of IL-17A in metastatic tissues." (PMID 38430256, 2024). "Mechanistic assays manifested that Oct4 binds to and transcriptionally activated IL-17A in cervical cancer cells." (PMID 38430256, 2024). "Injection of NSCLC and cervical cancer cells overexpressing IL-17A is more likely to induce tumorigenicity in immunodeficient mice than those of controls." (PMID 35665407, 2022). "They reported the AG frequencies of 45.7% and 46.4% in women with cervical cancer and healthy controls for IL17A SNPs, respectively." (PMID 36556060, 2022). "IL-17A rs2275913 could influence the expression of the IL-17A protein and trigger cell transformation and maintain the autonomous proliferation of the transformed cells, and thus increase the susceptibility of cervical cancer, especially in HPV infection individuals." (PMID 36300118, 2022). "Since we have shown by IHC that IL-17 is mainly expressed by neutrophils in cervical cancer, this suggests that IL17A RNA expression is primarily derived from Th17 cells." (PMID 25889974, 2015). "As overexpression of MMPs play an important role in cancer metastasis, the role of IL-17A on MMPs expression in cervical cancer cell lines (C33A and Caski) was investigated." (PMID 25250801, 2014). "Wound healing and matrigel transwell assays were used to examine the effect of IL-17A on cervical cancer cell migration and invasion by a panel of cervical cancer cell lines." (PMID 25250801, 2014). "To further define the point in the p38/NF-κB signal pathway at which IL-17A regulates the invasion of cervical cancer cells, we treated cervical cancer cells with SB203580(a p38 inhibitor) and PDTC(a NF-κB inhibitor), and analyzed the invasive ability." (PMID 25250801, 2014). "Here, we revealed that IL-17A significantly promoted the invasive and metastatic ability of cervical cancer cells by regulating MMP/TIMP balance via activating the p38/NF-κB signal pathway." (PMID 25250801, 2014). "To further clarify possible mechanism(s) of IL-17A in the promotion of cervical cancer cell invasion, we investigate the effect of IL-17A on the phosphorylation of p38." (PMID 25250801, 2014). "Association study was further applied to investigate the clinical significance of IL-17A expression in 50 cervical cancer specimens." (PMID 25250801, 2014). "We aimed to examine the effect of IL-17A on the invasion of cervical cancer cells and study its related mechanisms." (PMID 25250801, 2014). "Further studies in different population and with a larger size of samples are needed to identify the association between the IL17A and IL17F genes and the risk of cervical cancer." (PMID 23049595, 2012). "In this study, we aimed to determine the association between the polymorphisms of IL17 (IL17A and IL17F) and the risk of cervical cancer in Chinese women." (PMID 23049595, 2012). "In the present study, we analyzed two single-nucleotide polymorphisms (SNPs) in the IL17A (rs2275913) and IL17F (rs763780) in 311 cervical cancer patients and 463 controls using TaqMan assays." (PMID 23049595, 2012). "The regulatory mechanism between Oct4 and IL-17A in cervical cancer was further estimated." (PMID 38430256, 2024).
cervical carcinoma (continued). "IL-17A rs3748067 has been studied in cervical cancer several times." (PMID 38816694, 2024). "IL-17A expression and concentration were high in metastatic tissues and cells of cervical cancer." (PMID 38430256, 2024). "IL-17A was found to facilitate M2 macrophage polarization in cervical cancer." (PMID 38430256, 2024). "Furthermore, Oct4 promoted cervical cancer cell malignant phenotype and M2 macrophage polarization by activating the p38 pathway that, in turn, upregulated IL-17A." (PMID 38430256, 2024). "Next, the significant positive regulation between Oct4 and IL-17A in cervical cancer was confirmed." (PMID 38430256, 2024). "Furthermore, we found that IL-17A secreted by cervical cancer cells facilitated macrophages mediating the promotion on cell proliferative, migratory, and invasive capabilities." (PMID 38430256, 2024). "We therefore estimated the correlation between Oct4 and IL-17A in cervical cancer patients." (PMID 38430256, 2024). "In the next step, we wanted to investigate whether IL-17A secreted by cervical cancer cells is conducive to macrophage-mediated facilitation of cell malignant phenotype." (PMID 38430256, 2024). "Furthermore, IL-17A facilitated the macrophage-mediated promotion of cervical cancer cell proliferative, migratory, and invasive capabilities." (PMID 38430256, 2024). "Similarly, in another study, it was shown that IL-17A accelerated cervical cancer development by enhancing MMP expression." (PMID 38430256, 2024). "Moreover, we found that there is a significantly greater transcription level of IL-17A in cervical carcinoma (CESC) tissues than in normal tissues." (PMID 38816694, 2024). "Previous studies showed that IL-17A promotes cell proliferation in cervical cancer." (PMID 34094965, 2021). "In conclusion, the effect of IL-17A on cervical cancer cell invasion and metastasis may lead to the identification of new diagnostic markers and therapeutic targets." (PMID 25250801, 2014). "But up to now, little is known about the effect of IL-17A on cervical cancer progression." (PMID 25250801, 2014). "IL-17A could promote the migration and invasion of cervical cancer cell via up-regulating MMP2 and MMP9 expression, and down-regulating TIMP-1 and TIMP-2 expression via p38/NF-κB signal pathway." (PMID 25250801, 2014). "IL-17A mRNA expression was measured in 50 cervical cancer tissues by real-time PCR." (PMID 25250801, 2014). "In the present study, we found that IL-17A could enhance the migration and invasion abilities of cervical cancer cells." (PMID 25250801, 2014). "Correlation of IL-17A expression with clinicopathological features in 50 cervical cancer patients." (PMID 25250801, 2014). "Thus, Oct4 was indicated to transcriptionally activate IL-17A in cervical cancer cells." (PMID 38430256, 2024). "Therefore, we hypothesize that Oct4 can regulate cervical cancer development by binding IL-17A to modulate p38 pathway, and that Oct4 transcriptionally activates IL-17A to orchestrate M2 macrophage polarization and cervical cancer metastasis." (PMID 38430256, 2024). "Therefore, we speculate that high expression of LINC00673 in cervical cells may lead to the upregulation of IL-17A, and sustained IL-17A may promote the immune tolerance of mutant cells, leading to the occurrence of cervical cancer." (PMID 34094965, 2021). "In addition, western blot analysis revealed that the pre-treatment of SB203580 and PDTC abrogated the upregulation of MMP2 and MMP9 induced by IL-17A, further demonstrating that IL-17A regulated MMPs expression and invasion of cervical cancer cells via activating p38/NF-κB signal pathway." (PMID 25250801, 2014). "IL-17A may be a potential target to improve the prognosis for patients with cervical cancer." (PMID 25250801, 2014). "Here, we showed that IL-17A could promote the migration and invasion of cervical cancer cells." (PMID 25250801, 2014).
cervical carcinoma (continued). "However, it remains unknown whether genetic polymorphisms in IL17A and IL17F influence the risk of cervical cancer development." (PMID 23049595, 2012). "We found little MTA1 staining and few IL-17A-positive cells in normal cervical tissues, however, MTA1 staining and number of IL-17A-positive cells were increased in CIN and cervical cancer tissues." (PMID 31281798, 2019). "After treating with IL-17A, the expression of MMP2 and MMP9 proteins in cervical cancer cell lines (C33A and Caski) was increased, meanwhile the expression of TIMP-1 and TIMP-2 proteins was decreased." (PMID 25250801, 2014). "In addition, we found that ICA inhibited cervical cancer SiHa cells proliferation, migration, invasion, and the expression levels of TGF-β1, TNF-α, IL-6, IL-17A, and IL-10, as well as promoted cell apoptosis." (PMID 33849528, 2021). "In the present study, the results showed that the SNP rs2275913 of IL17A, but not the SNP rs763780 of IL17F was associated with the susceptibility of cervical cancer." (PMID 23049595, 2012). "Nevertheless, it is not yet known whether IL-17A facilitated cervical cancer development via inducing M2 macrophage polarization." (PMID 38430256, 2024). "Nevertheless, it is not yet known whether IL-17A facilitates cervical cancer development by inducing M2 macrophage polarization." (PMID 38430256, 2024). "In addition, treatment of cervical cancer cells with the pharmacological p38/NF-κB signal pathway inhibitors, SB203580 and PDTC, potently restored the roles of invasion and upregulation of MMPs induced by IL-17A." (PMID 25250801, 2014). "However, the relationship between Oct4 and IL-17A in cervical cancer has not yet been investigated." (PMID 38430256, 2024).
eosinophilia (59 papers, 2008 to 2026). "One study demonstrated that a hybrid subset of pathogenic ST2+ ILC2s that produced both IL-13 and IL-17A promoted increased lung eosinophilia after exposure to protease allergen." (PMID 40777291, 2025). "Rather, a combination of both TNFα and IL-17A are required to get maximal neutrophil recruitment, whereas the production of IL-17A alone was associated with a more pronounced eosinophilia." (PMID 21936897, 2011). "Together, our findings suggest that IL-18 signaling prevents IL-17A production from ILC2s and subsequent eosinophilia in vivo." (PMID 40777291, 2025). "We showed that IL-18 is induced by Alternaria exposure and attenuates eosinophilia and production of IL-17A production in lung ILCs." (PMID 40777291, 2025). "As expected, there was an increase in lung ILC type 2 cytokine and IL-17a production and eosinophilia in Rbm3−/− mice compared to WT mice." (PMID 35908044, 2022). "In our studies, blockade of IL-10 in conjunction with PZQ treatment led to an increase in eosinophilia and adult worm-specific IL-4, IL-5, IFNγ and IL-17A." (PMID 21829367, 2011). "In this case, the marked elevation of anti-Dsg1, eosinophilia, and dermal eosinophilic infiltrate suggest that IL-17A inhibition may have downregulated the Th1/Th17 axis, relieving inhibition of Th2 cells and promoting IL-4/IL-13 elevation." (PMID 41000395, 2025). "As previously observed, the adoptive transfer of allergen-pulsed mDCs yields robust production of IFNγ and IL-17A and airway neutrophilia along with the typical Th2 cytokines and eosinophilia, a response which more closely resembles the mixed Th1/Th2/Th17 response observed in severe asthmatics." (PMID 21936897, 2011). "Thus, it is plausible that the increased ILC IL-17A production in the IL-18R−/− mice could drive increased lung eosinophilia." (PMID 40777291, 2025). "Following challenge with np-Der p1 protein, immunized mice exhibited reduced allergic responses, including lessened eosinophilia, decreased Th2 (GATA3+ and IL-5+IL-13+) and Th17 (IL-17A+) cell frequencies, and lowered mucus production." (PMID 40985871, 2025). "Accordingly, there was increased expression of Muc5ac, pro-Th2 and Th17 cytokine (e.g., Il13, Il33 and Il17a), increased BALF eosinophilia, as well as increased genes involved in epithelial repair responses in the lungs (e.g. Egfr and Tff2)." (PMID 31089182, 2019). "We further observed an early increase in dual production of IL-5 and IL-17A in ST2+ ILCs followed by enhanced lung eosinophilia in the absence of IL-18R." (PMID 40777291, 2025). "IL-17A induced by NE vaccination improved protection to RSV without increased lung pathology or eosinophilia upon challenge in mouse and cotton rat models, further supporting this." (PMID 34603303, 2021). "Indeed, depletion of CD4+ cells just before final allergen challenge or genetic ablation of IL-17A/F compromised CXCL5 accumulation and allergic neutrophilia, but not eosinophilia, in the airways of LH mice despite their extensive inhalation experience." (PMID 39965565, 2025). "(2011), IL-17A induced locally in the lungs and BAL by a nano emulsion-based inactivated RSV immunization improved protection against RSV without increasing lung pathology or eosinophilia upon challenge in mouse and cotton rat models." (PMID 40176816, 2025). "As dexamethasone reduced eosinophilia and Th2 cytokines but could not diminish neutrophilia and IL-17A secretion, it is possible that steroid resistance of AHR is related to the IL-17-induced neutrophilic and Th17 contingents." (PMID 33312170, 2020).